MERTK (MER proto-oncogene, tyrosine kinase)
Diseases named in the same sentence as MERTK in open-access papers (continued):
Sharing a sentence is not in itself a finding about the gene and the disease.
Cirrhosis (11 papers, 2018 to 2023). A chronic disorder of the liver in which liver tissue becomes scarred and is partially replaced by regenerative nodules and fibrotic tissue resulting in loss of liver function. "Second, the limited sample size of this study could limit the ability to find significance in some comparisons, such as the association between MERTK rs4374383 and the progression to cirrhosis." (PMID 30477195, 2018). "When comparing peripheral circulating monocytes in stable cirrhosis conditions to PMs of patient with ACLF increased immunoregulatory MERTK-expression population was found, indicating a more suppressive phenotype of PMs in ACLF patients." (PMID 36926073, 2022). "Another TAM receptor family member, MERTK was found to be up-regulated on circulating monocytes in the stage of AD/ACLF in cirrhosis patients." (PMID 36926073, 2022). "Given the distinct and reciprocal expression profiles of AXL and MERTK in cirrhosis, it further needs to be addressed which receptor to target at which stage of disease and in which compartment." (PMID 31822557, 2020). "By contrast, CD14+HLA-DR+MERTK+ monocytes remained undetectable in stable cirrhosis and emerged upon AD." (PMID 31822557, 2020). "This underlines the distinct and counter-regulatory roles of AXL and MERTK in different phases of cirrhosis and inflammation." (PMID 31822557, 2020). "Among individuals with different degrees of NAFLD (steatosis/fibrosis/cirrhosis), only cirrhotic patients displayed increased Gas6 and MERTK serum levels." (PMID 31583026, 2019). "Similarly, we observed low AXL but increased MERTK expression on peritoneal macrophages of decompensated cirrhosis patients with ascites." (PMID 37004869, 2023). "MERTK-expressing cells were increased in patients with advanced cirrhosis compared with controls." (PMID 37004869, 2023). "By contrast, MERTK expression has been identified as a marker both for immunosuppressive circulating monocytes and for macrophages in the liver, peritoneum and mesenteric lymph nodes in acute decompensation of cirrhosis (AD/ACLF)." (PMID 36926073, 2022). "Moreover, macrophages expressing MERTK accumulated in the liver, but also the peritoneal cavity and mesenteric lymph nodes, in patients with decompensated cirrhosis and ACLF." (PMID 36926073, 2022). "AXL and MERTK expression on circulating monocytes modulated immune responses in patients with cirrhosis (CD14+HLA-DR+AXL+) and acute-on-chronic liver failure (CD14+MERTK+)." (PMID 37004869, 2023). "Ex vivo data obtained from patients at different stages of cirrhosis support the potential strategy of targeting TAM receptors AXL and MERTK." (PMID 36926073, 2022). "Therefore, MERTK and its variants could act as central players in the control of apoptosis, immune response, HSC activation, and steatosis modulation, e.g., all factors involved in the pathogenesis of NAFLD and its fibrotic progression to steatohepatitis and cirrhosis." (PMID 31583026, 2019). "Our data do not support the assumption that in cirrhosis AXL+ macrophages may be transformed towards MERTK+ macrophages, because we did not see that loss of AXL would lead to an up-regulation of MERTK on primary human macrophages ex vivo (data not shown)." (PMID 37004869, 2023). "Immune defects permitting BT were also observed in mesenteric lymph nodes from patients with decompensated cirrhosis, where circulation-derived subcapsular sinus and medullary cord macrophages expressed the immune-suppressive marker MERTK, compared to non-cirrhotic controls." (PMID 33868313, 2021). "In CLD with and without compensated cirrhosis, however, MERTK and TYRO3 expressions were sparse." (PMID 31822557, 2020).
COVID-19 (11 papers, 2020 to 2025). A disease caused by infection with severe acute respiratory syndrome coronavirus 2. "Increased MERTK shedding could result in reduced surface expression and loss of MERTK signaling, which could play a central role in the hyper inflammation observed in severe COVID-19." (PMID 35839768, 2022). "In contrast, IL1B and IL18 transcripts were expressed in the SPP1/MERTK+ (inflammatory monocyte-derived) macrophage cluster in the COVID-19-infected samples." (PMID 37737611, 2023). "Phagocytes in the lungs of COVID-19 patients also expressed lower protein levels of MERTK." (PMID 35666101, 2022). "An interesting aspect for analysis is if dexamethasone upregulation of MERTK and the consequent enhancing of innate anergy could play a positive role in COVID-19." (PMID 32998369, 2020). "The pleiotropic roles of MERTK in the regulation of lung endothelial integrity, coagulation, and inflammation suggest that impaired MERTK signaling may be a central component of the pathogenesis of severe COVID-19." (PMID 35839768, 2022). "In human COVID-19, expression of IL1B and IL18 shifted from mostly alveolar macrophages to SPP1/MERTK+ macrophages." (PMID 37737611, 2023). "The scRNAseq data show that, in healthy human BALF, the FABP4+ macrophages express the TAM receptor AXL and the ligand for the TAM receptor MerTK (PROS1) and that these were profoundly repressed in severe COVID-19." (PMID 34143756, 2021). "However, the reduced PROS1, which is the preferred activating ligand for MerTK, and the fewer homeostatic resident AMs in severe COVID-19 might enable unrestricted proinflammatory cytokine production by locally differentiated MerTK-expressing FCN+ and FCN+SPP1+ macrophages." (PMID 34143756, 2021). "Of note, dexamethasone, which has been approved as COVID-19 treatment for seriously ill patients, is a potent activator of the PROS1/MERTK axis." (PMID 32998369, 2020). "PROS1 is an agonist for tyrosine kinase receptors MERTK and TYRO3, through which it limits the activation of innate immune responses, vascular permeability, response to cell damage, and coagulation-related pathologies in COVID-19." (PMID 40980495, 2025). "The dysregulation of blood coagulation during COVID-19 results in depleted circulating PROS1 levels, which can consequently contribute to cytokine storm by reducing the immunosuppressive action of MERTK in macrophages and diminishing intrinsic PROS1 anticoagulant function." (PMID 40980495, 2025). "Genotyping of our patients show that the polymorphic assessment for MERTK does not affect neither the rate of infection, the genotypes being in Hardy-Weinberg equilibrium, nor the likelihood of a severe outcome of COVID-19." (PMID 34249902, 2021). "In fact, from the group comparison of COVID-19 vs. non-COVID-19, the authors identified 14 specific inflammatory proteins that can be related to SARS-CoV-2 infection, namely CXCL5, CXCL10, CXCL11, Gal-9, IL-18, IL-18R1, IFNγ, LIF-R, MCP-2, MCP-3, MERTK, MMP-1, PD-L1, and TNF." (PMID 35269564, 2022).
acute liver failure (10 papers, 2018 to 2023). Rapid deterioration of liver function causing encephalopathy and coagulopathy. "Existing studies proved that loss of MerTK amplified the inflammatory response of LPS and macrophage MerTK promoted the dissolution of inflammation in acute liver failure." (PMID 36225585, 2022). "Fittingly, in MerTK-deficient mice acute liver failure (ALF) due to APAP administration is aggravated and associated with a reduced number of hepatic macrophages and increased MPO+ neutrophils." (PMID 31798592, 2019). "Interestingly, the expansion of MerTK-positive MoMFs is also evident in the liver of patients with acute liver failure and associates with a greater severity of liver injury and adverse clinical outcome." (PMID 34925367, 2021). "Secretory leukocyte protease inhibitor, an anti-inflammatory protein identified in mice and humans with acute liver failure, facilitates differentiation toward MerTK-positive restorative macrophages." (PMID 37082623, 2023). "Because MerTK is a phagocytic receptor that recognizes apoptotic cells, MerTK-positive macrophages promote resolution of liver inflammation and liver repair in acute liver failure by enhancing the clearance of apoptotic neutrophils." (PMID 37082623, 2023). "The expansion of MERTK-expressing monocytes and macrophages was moreover detected in acute liver failure and characterised by both suppressed immune responses and enhanced efferocytic capacities." (PMID 31822557, 2020). "In patients with acute liver failure MerTK-expressing macrophages expand, and migrate to the necrotic areas in the liver." (PMID 31798592, 2019). "Macrophage MerTK also relieved liver inflammation in acute liver failure." (PMID 36225585, 2022). "In addition, CD14+HLA-DR+MERTK+ cells were abundant in the circulation and the liver in acute liver failure where they were characterised as resolution-type monocytes/macrophages." (PMID 31822557, 2020). "Alternatively, resident KCs may upregulate MerTK expression upon APAP overdose, as secretory leucocyte protease inhibitor (SLPI), produced in acute liver failure, was shown to induce MerTK expression in monocytes and hepatic macrophages." (PMID 34177948, 2021).
Arthritis (10 papers, 2017 to 2025). Inflammation of a joint. "To gain further knowledge of the upstream and downstream pathways linked to Axl and MerTK, we built an Axl and a MerTK module composed of predicted gene partners and assessed their expression in the early arthritis RNA-seq dataset." (PMID 38493215, 2024). "MerTK-deficient mice show ed exacerbated arthritis pathology." (PMID 38066599, 2023). "MerTK is a crucial tyrosine kinase for the macrophage differentiation towards an anti-inflammatory/resolving phenotype and its deficiency exacerbates the severity of collagen-induced arthritis, while MerTK signalling activation reduces it in this arthritis model." (PMID 38283352, 2023). "Next, we quantified the soluble extracellular domain of Axl (sAxl), MerTK (sMerTK), and their ligand Gas6 in the SF obtained at the same time as the synovial biopsy in a subset of early arthritis untreated patients." (PMID 38493215, 2024). "A protective role for MerTK has also been described in experimental models of arthritis and confirmed in micromasses of human monocytes and synovial fibroblasts." (PMID 38493215, 2024). "In turn, MerTK plays a protective function in murine arthritis models, is expressed by synovial tissue macrophages and is linked to remission in patients with RA." (PMID 38283352, 2023). "Reference mapping showed that the majority of ICI-arthritis myeloid cells mapped onto four RA myeloid clusters: IL1B + FCN1 + HBEGF+, STAT1+ CXCL10+, SPP1+, and MERTK+ HBEGF+ clusters." (PMID 40662950, 2025).
Autoimmunity (10 papers, 2013 to 2025). The occurrence of an immune reaction against the organism's own cells or tissues. "In humans, mutations in efferocytic receptors, especially in MERTK and its opsonins, are associated with a similar increase in the risk of autoimmune disorders including multiple sclerosis and rheumatoid arthritis, highlighting the importance of efficient efferocytosis in limiting autoimmunity." (PMID 33959122, 2021). "We identified new suggestive associated loci of AAU, including MERTK, which was reported to be involved in the development of autoimmunity, indicating the potential role of MERTK in the etiology of AAU." (PMID 32492107, 2020). "The downregulation of immune responses by MerTK signaling was an important regulatory mechanism to prevent the rise of autoimmunity." (PMID 24741600, 2014). "Nonetheless, association of these traits suggests the potential of MerTK+/high M2c macrophages for use in ACT, particularly for autoimmune conditions such as rheumatoid arthritis, inflammatory bowel disease, type-I diabetes mellitus, and AGE/RAGE signaling pathway in diabetic complications." (PMID 40206211, 2025). "In physiological conditions, the interaction between PROS1 and MERTK is essential for efferocytosis—the clearance of apoptotic cells by phagocytes—which is critical for maintaining tissue homeostasis and preventing chronic inflammation and autoimmunity." (PMID 39535659, 2025). "Growth Arrest-Specific 6 (Gas6) and Tyro3, Axl, and MerTK (TAM) receptors are involved in multiple biological processes, including modulation of the immune response, phagocytosis, apoptosis, fibrosis, inflammation, cancer development, and autoimmune disorders." (PMID 39057085, 2024). "Mice lacking MERTK develop mild autoimmunity while mice lacking all three TAM kinases develop severe autoimmunity, partially caused by hyperactivation of antigen-presenting cells and hyperproliferation of lymphocytes." (PMID 31805065, 2019). "Although a rationale for using TZDs in SLE autoimmunity would be conversion of M2b macrophages into M2a cells and promotion of PPAR-γ-dependent efferocytosis, the inhibitory role herein shown on M2c differentiation and on MerTK expression should be taken into account." (PMID 25972766, 2015). "Alternatively, excess ectodomain shedding of MerTK and CD163 by ADAM-17 may account for a functional impairment of M2c monocytes/macrophages and could itself contribute to chronic inflammation, defective clearance of early ACs and autoimmunity." (PMID 24325951, 2013).
myocardial infarction (10 papers, 2014 to 2025). Gross necrosis of the myocardium, as a result of interruption of the blood supply to the area, as in coronary thrombosis. "It is worth noting that in myocardial infarction, a leading cause of death worldwide, MerTK-mediated efficient clearance of dying cardiomyocytes is beneficial for restoration of cardiac function." (PMID 38341954, 2024). "It is evident that MerTK contributes to the efferocytosis process of macrophages in the context of myocardial infarction." (PMID 41590849, 2025). "An abnormally low expression of MerTK is found in myocardial infarction and stable angina, and intracranial aneurysm." (PMID 38341954, 2024). "Notably, the expression of ADAM17, an exfoliating protease, is upregulated during myocardial infarction, resulting in the solubilization of MerTK and its transformation into a soluble Mer." (PMID 41590849, 2025). "Maintaining elevated MerTK expression, potentially through extracellular vesicles secreted by cardiosphere-derived cells, could enhance efferocytosis efficacy and improve outcomes following myocardial infarction." (PMID 39660125, 2024). "Recently, it was found that MerTK expression and ERK1/2 activation are essential for the functional maturation of reparative macrophages after myocardial infarction." (PMID 38334600, 2024). "In blood vessel diseases compared with normal control, MerTK expression is 14.2 % (p = 0.0002) higher in carotid stenosis but significantly lower in coronary artery disease (CAD), CAD coupled to myocardial infarction or stable angina, Cohn's disease, intracranial aneurysm, and stable angina." (PMID 38341954, 2024). "In contrast, MerTK is lowly expressed in coronary artery disease, acute myocardial infarction, and nonischemic systolic heart failure." (PMID 38341954, 2024).
rheumatoid arthritis (10 papers, 2021 to 2026). A chronic, systemic autoimmune disorder characterized by inflammation in the synovial membranes and articular surfaces. "The TAM tyrosine kinases, Axl and MerTK, have been implicated in rheumatoid arthritis (RA)." (PMID 38493215, 2024). "Since then, Axl and MerTK, in particular, have been implicated in the pathogenesis of human autoimmune diseases, including rheumatoid arthritis (RA); however, the exact contribution of individual TAMs toward the regulation of inflammation and clinical response to therapy remains to be elucidated." (PMID 38493215, 2024). "In embryo blood vessels, MerTK expression is 11.8 % (p = 0.0022) lower in rheumatoid arthritis than in the control group." (PMID 38341954, 2024). "The TAM tyrosine kinases, Axl and MerTK, play an important role in rheumatoid arthritis (RA)." (PMID 38493215, 2024). "Three tissue macrophage clusters (M-0, M-1 and M-2) were abundant in both osteoarthritis and rheumatoid arthritis synovium and expressed the phagocytic factors CD206 (also known as macrophage mannose receptor (MMR)) and CD163 and MERTK, suggesting a homeostatic debris-clearing function." (PMID 37938773, 2023). "More recent studies using healthy and rheumatoid arthritis (RA) synovium have proposed new nomenclature for different synovial macrophage subsets, including CX3CR1+/TREM2+ lining macrophages and subsets based on the expression of CD163, CD206, and MERTK." (PMID 37612718, 2023).
autoimmune disease (9 papers, 2016 to 2026). A disorder resulting from loss of function or tissue destruction of an organ or multiple organs, arising from humoral or cellular immune responses of the individual to their own tissue constituents. "For example, Gal-3′s ability to mediate the clearance of apoptotic cells via MerTK implicates it as a role player in immune resistance and immunosuppression, contributing to conditions such as cancer and autoimmune diseases." (PMID 32664510, 2020). "In animal models it has been shown that the relationship of MERTK to autoimmune disease is complex, and in some cases dependent upon genetic background." (PMID 26990204, 2016). "Additionally, overexpressed genes such as IKAROS family zinc finger 3 (IKZF3), MER proto-oncogene, tyrosine kinase (MERTK), and Fc receptor-like 5 (FCRL5) all have risk alleles associated with MS or other autoimmune diseases." (PMID 39596026, 2024). "With the current interest in MERTK as a therapeutic target in autoimmune diseases, and indeed its use as a marker of tolDCs in human trials, it is important to understand the mechanisms by which MERTK signalling could promote a tolerogenic phenotype in DCs." (PMID 37958886, 2023).
colorectal cancer (9 papers, 2016 to 2024). A primary or metastatic malignant neoplasm that affects the colon or rectum. "A similar effect was detected in a colorectal cancer study, in which knockdown of MerTK enhanced the antiproliferative effect of 5‐FU in HCT116 cells." (PMID 38545840, 2024). "In colorectal cancer, the upregulation of MERTK has been considered a predictive marker for resistance towards MEK1/2 inhibitors in a large clinical cohort." (PMID 33562150, 2021). "In colorectal cancer, the upregulation of MERTK has been considered as a predictive marker for resistance towards MEK1/2 inhibitors in a large clinical cohort." (PMID 33562150, 2021). "A lipid nanoparticle platform encapsulating siRNA for the phagocytic receptor MerTK (siMerTK) was found to selectively inhibit MerTK-mediated efferocytosis and exert therapeutic effects in both liver and peritoneal metastasis models of colorectal cancers." (PMID 38779685, 2024). "scRNA-seq in human and mouse colorectal cancer identified a population of C1QC+ TAMs, characterized by high levels of C1QA/B/C, TREM2, and MERTK expression, which were associated with potential recruitment and activation of T cells, phagocytosis, and better prognosis." (PMID 36240276, 2022). "Here we show that AXL, but not MERTK or TYRO3 expression is enhanced in late stage colorectal cancer (CRC) and AXL expression associates with a cell migration gene signature." (PMID 28727830, 2017). "Nevertheless, in gastrointestinal carcinomas, such as GC and colorectal cancer (CRC), patients with MerTK overexpression show a poor prognosis, while the underlying mechanism is still poorly studied." (PMID 38545840, 2024).